PTBP3 (polypyrimidine tract binding protein 3)
Diseases named in the same sentence as PTBP3 in open-access papers (continued):
Sharing a sentence is not in itself a finding about the gene and the disease.
cancer (24 papers, 2012 to 2025). A tumor composed of atypical neoplastic, often pleomorphic cells that invade other tissues. "PTBP3 is highly expressed in many cancers and is often associated with poorer survival outcomes." (PMID 40270362, 2025). "Among the PTBP family members, PTBP1 is most frequently linked with cancer, followed by PTBP3." (PMID 36203873, 2022). "The relationship between PTBP3 expression and cancer-associated fibroblasts was analysed." (PMID 35359851, 2022). "As an important member of the PTB family, PTBP3 has been reported to be overexpressed and play a role in the progression of various cancers." (PMID 38405614, 2024). "It is well known that metastasis and invasion are essential for cancer metastasis, we investigated the role of PTBP3 in RCC metastasis in vivo." (PMID 38405614, 2024). "The western blotting results revealed higher expression levels of PTBP3 in the cancer tissues than in their matched controls." (PMID 39116343, 2024). "While the overexpression of Ptbp3 is correlated with many cancer phenotypes, the knockdown or silencing of Ptbp3 has been shown to induce cell cycle arrest and apoptosis." (PMID 37628627, 2023). "The three main members of the PTBP family are PTBP1, PTBP2, and PTBP3, of which PTBP3 promotes the growth and metastasis of cancer cells and also prevents the degradation of mRNAs." (PMID 37631029, 2023). "The downregulation of Ptbp3 is also a positive sign for improving genome stability as overexpression is a highly reliable biomarker for cancers." (PMID 37628627, 2023). "Recent literature acknowledges the close relationship of PTBP3 with the progression of different malignant tumors." (PMID 32477006, 2020). "PTBP3 increases cancer cell proliferation and autophagic flux in response to hypoxic stress, which contributes to gemcitabine resistance." (PMID 31989778, 2020). "Among these genes, PTBP3 was reported to be a key cancer metastasis regulator in GC and selected for further validation." (PMID 32117452, 2020). "We also perform western blotting based on obtained 147 pairs of NSCLC samples, and reconfirmed the similar expression tendency of PTBP3 between cancer and normal tissues." (PMID 32477006, 2020). "These interactions support an open chromatin form for the PTBP3 locus in cancer cells and the three-dimensional structural model proposed in this paper." (PMID 30634466, 2019). "An improved understanding of the regulatory mechanism about PTBP3 in regulating cancer metastasis can provide critical information on how to block related processes in cancer progression." (PMID 31291975, 2019). "We observed a significant change in the PTBP3 mRNA levels in cancer cell lines versus normal cells, consistent with high expression in lung cancer and stomach cancer." (PMID 30634466, 2019). "To investigate the mechanism of higher level of PTBP3 in cancer cells, we examined chromatin interaction of the PTBP3 locus." (PMID 30634466, 2019). "Thus, we investigated the expression, function, and immune characterization of PTBP1, PTBP2, and PTBP3 in pan-cancer." (PMID 36203873, 2022). "Remarkably, PTBP1 on Th2 cells, PTBP2 on T helper cells and Tcm, and PTBP3 on T helper cells, Tcm, and Th2 cells may have broad positive regulatory effects in pan-cancer." (PMID 36203873, 2022). "PTBP1, PTBP2 and PTBP3 may be potential biomarkers for prognosis and immunotherapy in pan-cancer and may be novel immunotherapeutic targets." (PMID 36203873, 2022). "Additionally, PTBP3 expression was detected in 5 human CRC cell lines (HT-29, HCT116, SW480, SW620 and LoVo) and normal human colonic epithelial FHC cells, and PTBP3 expression was significantly higher in cancer cell lines than in FHC cells." (PMID 35136024, 2022). "Additionally, we also explored the role of PTBP3 expression in the proliferation and invasion of cancer cells." (PMID 32477006, 2020). "PTBP3 may play an emerging role in various cancer progressions." (PMID 35016691, 2022).
cancer (continued). "Therefore, it could be possible that the up‐regulation of PTBP3 leads to an imbalance of non‐coding transcriptional response in cancer cells." (PMID 31989778, 2020). "In addition, we determined the sensitivity of cancer cells to gemcitabine with differential levels of PTBP3 and whether autophagy and hypoxia affect gemcitabine resistance in vitro." (PMID 31989778, 2020). "PTBP3 may present an emerging role of in various cancer progressions." (PMID 31291975, 2019). "Therefore, we attempted to use the 3C technique to investigate whether the chromatin architecture of the PTBP3 gene regulates its expression at the transcriptional level in cancer cells." (PMID 30634466, 2019). "Moreover, accumulated evidence concerning PTBP3 in different cancer types has been reported." (PMID 29752441, 2018). "The PTBP3 protein mediates TGF-β-induced epithelial-to-mesenchymal transition and can serve as an immunomodulatory biomarker of cancer." (PMID 37113661, 2023). "Spearman correlation analysis on the pan-cancer dataset from cBioPortal yielded 926 mRNAs co-expressed with PTBP1, 657 mRNAs co-expressed with PTBP2, and 874 mRNAs co-expressed with PTBP3 (|R| ≥ 0.4, p < 0.05)." (PMID 36203873, 2022). "Thus, PTBP3 overexpression may upregulate Id1a expression and downregulate Id1b expression to attenuate the inhibition of Hes1 activity, which indirectly increases the activity of Hes1, leading to the inhibition of cancer cell differentiation." (PMID 32974175, 2020). "This study comprehensively and systematically analyzed the prognostic value, genetic variation, and signaling pathways of PTBP1, PTBP2, and PTBP3 and the correlation of PTBP expression with TILs, ICP, TMB, MSI, and drug sensitivity from a pan-cancer perspective." (PMID 36203873, 2022). "Moreover, PTBP3 contributes to therapeutic resistance to gemcitabine under hypoxia, implying a possibility that BCRT1 regulates the sensitivity of cancer cells to therapeutic agents." (PMID 34298879, 2021). "Since PTBP3 can activate the translation of HIF-1α mRNA, a BCRT1/PTBP3/HIF-1α feedback loop may control cancer progression." (PMID 34298879, 2021). "PTBP3 directly regulates the EMT process and cancer stem cells by binding to the 3′UTR of ZEB1." (PMID 34944712, 2021). "Collectively, our findings suggested that PTBP3 contributed to the progression of NSCLC and might serve as a potential target for anti-cancer therapy." (PMID 32477006, 2020). "However, mechanisms which regulate the PTBP3 expression in cancer cells have never been explored." (PMID 30634466, 2019).
PTBP3 also shares sentences with these, for which no sentence is quoted: infection (3 papers); adrenocortical carcinoma (2); breast invasive carcinoma (2); colon adenocarcinoma (2); epithelial ovarian cancer (2); amyotrophic lateral sclerosis (1); bladder cancer (1); cardiac hypertrophy (1); cardiomyopathies (1); cervical cancer (1); cyst (1); gynecological tumors (1); Hypertension (1); kidney disease (1); lentivirus infection (1); melanoma (1); neuroblastoma (1); oesophageal cancer (1); ovarian cancer (1); soft tissue sarcoma (1); squamous cell carcinoma (1); thyroid carcinoma (1).